PTCH1 (patched 1)
Diseases named in the same sentence as PTCH1 in open-access papers (continued):
Sharing a sentence is not in itself a finding about the gene and the disease.
Gorlin syndrome (continued). "Gorlin syndrome (basal cell nevus syndrome), an autosomal dominant condition, is associated with germline loss of the PTCH1 gene." (PMID 32296030, 2020). "Alterations of PTCH1 lead to constitutive activation of the hedgehog signaling pathway and germinal mutation of PTCH1 are linked to Gorlin syndrome (i.e., nevoid basal cell carcinoma syndrome)." (PMID 32759723, 2020). "This provides rationale for the future therapeutic trials of other tumors in the setting of PTCH1 loss, and it would be interesting to see how various types of tumors in Gorlin syndrome respond to the similar treatment." (PMID 32964316, 2020). "Of note, patients with SUFU mutations have an increased risk of developing medulloblastoma as compared to PTCH1 mutations in Gorlin-Goltz syndrome." (PMID 31533758, 2019). "Over 500 different PTCH1 mutations have been implicated in Gorlin syndrome (i.e., basal cell carcinoma and rhabdomyosarcoma), sporadic basal cell carcinoma, holoprosencephaly, keratocystic odontogenic tumors, and ocular developmental anomalies." (PMID 31362756, 2019). "Some of these genetic aberrations are the drivers of the heritable basal-cell nevus syndrome (Gorlin syndrome), in which patients inherit only one functional copy of genes encoding PTCH1." (PMID 31035664, 2019). "We tested this idea, first by transducing NES cells with MYCN and second by deriving NES cells from patients with Gorlin syndrome, bearing germline mutations in PTCH1, and in each case performing orthotopic transplantation in mice." (PMID 31204176, 2019). "Orthotopic transplantation of NES cells generated from Gorlin syndrome patients, who are predisposed to medulloblastoma due to germline-mutated PTCH1, also generated medulloblastoma." (PMID 31204176, 2019). "In fact, germline PTCH1 mutations underlie nevoid basal-cell carcinoma syndrome, also known as Gorlin Syndrome." (PMID 31362756, 2019). "This type of aberrant HH pathway activation was found for the first time in patients with Gorlin syndrome, a condition predisposing to cancer due to mutations in the PTCH1 gene." (PMID 30934935, 2019). "Gorlin syndrome is mainly caused by pathogenic germline variants in the tumour suppressor genes PTCH1 and SUFU, both regulatory genes in the hedgehog pathway." (PMID 31485359, 2019). "Although de novo mutations of the PTCH1 gene occur in almost 50% of Gorlin syndrome cases, there are a few recurrent mutations." (PMID 29498494, 2018). "The link between Hh signaling and tumorigenesis was first discovered in patients with Gorlin syndrome, which was characterized by a loss of Ptch1 heterozygosity." (PMID 30110910, 2018). "The loss of PTCH1 in Gorlin syndrome is associated with a range of rare tumours in addition to BCC and MB, including fetal rhabdomyoma." (PMID 30068568, 2018). "Two different heterozygous mutations in the PTCH1 gene were identified in two patients with Gorlin syndrome." (PMID 29575684, 2018). "Six major criteria by Kimonis and the PTCH1 mutation in the four study subjects with Gorlin syndrome." (PMID 28915250, 2017). "First, the four individual patients who qualified the diagnostic criteria for Gorlin syndrome had novel PTCH1 gene mutations." (PMID 28915250, 2017). "Heterozygous germline PTCH1 mutations have been detected in patients with Gorlin syndrome and the loss of function PTCH1 mutations are predicted to reduce suppression of Smoothened (SMO)." (PMID 28915250, 2017). "A previous study reported that Ptch1-deficient (Ptch1+/−) mice and Gorlin syndrome patients exhibited increased bone mass as adults, suggesting that the patients’ stem cells were hypersensitive to osteogenic induction." (PMID 29088246, 2017). "Several mutations in PTCH1 have been reported that mention it as the causative gene of Gorlin syndrome by conventional Sanger sequencing." (PMID 28915250, 2017).
Gorlin syndrome (continued). "A marker at 9q22.32 is located at the intronic region of PTCH1, mutations of which have been identified in patients of Gorlin syndrome with CL/P as one of its clinical manifestations." (PMID 28232668, 2017). "The initial link between HH signaling and human cancers was established when mutations in human PTCH1 were found to be associated with a rare hereditary disease called Gorlin's syndrome." (PMID 28243259, 2017). "Although the analysis of large genes such as PTCH1 is technically challenging, few reports have described the genome-wide characterization of mutation analysis of Gorlin syndrome." (PMID 28915250, 2017). "We demonstrated multiple mutations of Hh-related genes in addition to PTCH1, which possibly act in an additive or multiplicative manner and lead to Gorlin syndrome." (PMID 28915250, 2017). "We performed an exome analysis to detect mutations in the predicted gene PTCH1, in patients with Gorlin syndrome." (PMID 28915250, 2017). "The hypersensitivity to radiation is also a peculiar feature of the Gorlin syndrome, an autosomal dominant disorder due to a germline inactivation of the PTCH1 gene, and individuals affected have a higher risk than the general population of developing tumors." (PMID 27626168, 2016). "This was first demonstrated when PTCH1 mutations were found to be the cause of the basal cell nevus syndrome (BCNS) (Gorlin Syndrome), a syndrome in which patients readily develop BCCs." (PMID 27462278, 2016). "Usually the patients with interstitial deletions involving 9q22 had a loss of the PTCH1 gene (chr9: 98,205,265–98,279,247), and thus revealed typical features of Gorlin syndrome." (PMID 27516809, 2016). "Previous studies revealed a lack of genotype–phenotype correlations between mutations in PTCH1 and the major clinical features of Gorlin syndrome." (PMID 26544948, 2015). "Collectively, the Gorlin syndrome phenotypes were consistent with heterozygous PTCH1 defects caused by various types of mutations or deletions in all investigated families with this disease." (PMID 26544948, 2015). "Numerous germline PTCH1 mutations, including nonsense, missense, frameshift, and splicing mutations as well as gross insertions and deletions, have been reported in Gorlin syndrome patients." (PMID 26544948, 2015). "Heterozygous germline PTCH1 mutations have been found in patients with Gorlin syndrome, and the spectrum of associated features is thought to arise from PTCH1 malfunction." (PMID 26544948, 2015). "Accordingly, we concluded that p.I531Gfs*92 was a novel PTCH1 mutation causative of Gorlin syndrome in family D." (PMID 26544948, 2015). "Patients with Gorlin syndrome (or basal cell nevus syndrome) have inherited inactivating mutations in Ptch1, leading to constitutively active Hh signaling in the absence of Hh ligands." (PMID 25955804, 2015). "Patients with basal cell nevus syndrome (BCNS or Gorlin syndrome) carry germline mutations in one allele of PTCH1 that leads to unrestrained activation of GLI1 and an ensuing predisposition for spontaneous tumorigenesis." (PMID 26197339, 2015). "The RND/sterol-sensing domain is criticalto Ptch1 function as multiple inactivating mutations in this region have been foundin Drosophila as well as in Gorlin syndrome patients." (PMID 24925320, 2014). "As expected for a classical tumor suppressor gene, PTCH1 was found to be mutated in Gorlin syndrome and many other cancers." (PMID 23826113, 2013). "PTCH1 mutations lead to complex syndromes such as the Gorlin syndrome (GS) also named nevoid basal cell carcinoma syndrome (NBCCS, OMIM #109400)." (PMID 24369017, 2013).
Gorlin syndrome (continued). "In fact, heterozygous, germline loss-of-function mutations in PTCH1 result in a different disorder, Basal Cell Nevus Syndrome (also called Gorlin syndrome)." (PMID 24244464, 2013). "We report here the case of a female proband with CALS associated to Nevoid Basal Cell Carcinoma Syndrome (NBCCS) with known PTCH1 germline mutation (C.1348-2A>G) who had been misdiagnosed with NF1 in her childhood because of 5 CALS and cutaneous nodules." (PMID 23107377, 2012). "Ptch1 mutations occur in the Gorlin syndrome-associated cancers basal cell carcinoma (BCC) and medulloblastoma." (PMID 22923130, 2012). "The initial link between Hedgehog signalling and human cancers was established when mutations in human PTCH1 were found to be associated with a rare hereditary disease called Gorlin's syndrome." (PMID 22550422, 2012). "Individuals with germline mutations in PTCH1 (Gorlin syndrome) are susceptible to multiple malignancies such as basal cell carcinoma (BCC), medulloblastoma, and to a lesser extent RMS." (PMID 22619564, 2012). "Currently, this disorder, resulting from mutations in the PTCH1 gene, is called the nevoid basal cell carcinoma syndrome (NBCCS), as Professor Gorlin suggested." (PMID 19032739, 2008). "As the primary Hh receptor, Ptch1 loss‐of‐function mutations autonomously activate both canonical and non‐canonical signalling, manifesting clinically as Gorlin syndrome (characterised by BCCs and medulloblastomas) and skeletal abnormalities, including craniosynostosis and osteoarthritis." (PMID 40857061, 2025). "LoF variants in PTCH1 are associated with basal cell nevus syndrome 1 (MIM #109400)." (PMID 40577202, 2025). "Additionally, Basal Cell Nevus Syndrome (Gorlin syndrome), which arises from mutations in PTCH1, an integral component of the Hedgehog signaling pathway, also predisposes individuals to NMSC." (PMID 39896186, 2024). "This emphasis is attributed to the association between PTCH1 and Gorlin syndrome." (PMID 38534460, 2024). "Indeed, inherited mutations in PTCH1 lead to Gorlin Syndrome (nevoid basal-cell carcinoma syndrome), a condition associated with development of multiple BCCs, particularly at a young age." (PMID 38954315, 2024). "This suggests that sporadic fibromas with 9q (PTCH1 location) alterations (LOH/CNA) could arise through similar genetic pathways to fibromas associated with Gorlin syndrome." (PMID 38136408, 2023). "However, patients with mutated PTCH2 displayed milder phenotypes of Gorlin syndrome when compared against PTCH1 and SUFU-related diseases." (PMID 36937440, 2023). "In Gorlin syndrome, a PTCH1 mutation on chromosome 9 is frequently identified." (PMID 37887561, 2023). "Gorlin syndrome (GS), or nevoid basal cell carcinoma syndrome, is caused by pathogenic variant in the PTCH1 tumor suppressor gene and characterized by basal cell carcinomas (BCCs), keratocystic odontogenic tumors of the jaw, medulloblastomas, and other cutaneous and skeletal features." (PMID 35720808, 2022). "In addition, 5% of all OKCs occur as part of nevoid basal cell carcinoma syndrome (NBCCS) caused by PTCH1 mutation." (PMID 36242048, 2022). "Gorlin-Goltz syndrome (GS) is an inherited disease characterized by predisposition to basal cell carcinomas (BCCs) and various developmental defects, whose numerous disease-causing PTCH1 mutations have been identified in the hedgehog (Hh) signaling pathway." (PMID 35932013, 2022).
Gorlin syndrome (continued). "Indeed, case 17 with global developmental delay has a NALCN missense variant that matches with the CLIFAHDD syndrome (# 616266) overlapping patient’s phenotype, and case 18 was with a PTCH1 frameshift variant associated with Gorlin syndrome (#109400)." (PMID 33337535, 2021). "Patient P4 presents, in both tumors, the same variant in PTCH1 gene, detected at a high frequency of reads (51.3% and 63.8%), thus suggesting that it could potentially be a germline variant involved in Gorlin syndrome associated with BCC in patient P4." (PMID 34284772, 2021). "Gorlin syndrome, or basal cell nevus syndrome, is a hereditary disease related to the mutations (more than 100 gene mutations have been reported) of patched 1, patched 2 and PTCH2, and SUFU genes, characterized by systemic and diverse developmental abnormalities and neoplastic lesions." (PMID 33809659, 2021). "In addition, familial loss-of-function mutations in the human Hedgehog signaling pathway gene PTCH1 have been implicated in basal cell nevus syndrome, which leads to basal cell carcinoma." (PMID 32579612, 2020). "Gorlin syndrome is caused by mutations in the PTCH1 gene, a human homologue of Drosophila patched." (PMID 32436863, 2020). "Characterized by developmental abnormalities and distinct postnatal cancer occurrence including medulloblastoma (1–2% of cases) and rhabdomyosarcoma (0.5% of cases), Gorlin syndrome primarily results from inactivating PTCH1 mutations on chromosome 9, leading to SMO hyperactivity." (PMID 32957513, 2020). "However, we assessed the PTCH1 variant to be a less likely candidate as a mutation in this gene would cause Gorlin syndrome (MIM 601309) with features including multiple nevoid basal-cell epitheliomas, jaw cysts, and bifid ribs." (PMID 32234057, 2020). "GSE1, also known as KIAA0182, has been shown to possess oncogenic properties in human breast cancer cells and gastric cancer and accelerates tumorigenesis in neuroepithelial stem cells of Gorlin syndrome patients, who are predisposed to medulloblastoma due to PTCH1 mutation." (PMID 31470906, 2019). "Furthermore, “one-hit” PTCH1 inactivation has been described in up to one-third of patients with nevoid basal cell carcinoma syndrome (NBCCS) who have mono-allelic PTCH1 mutations." (PMID 31362756, 2019). "It was first characterized by identification of a germ line mutation in the patched homolog 1 (PTCH1) gene in basal cell nevus syndrome, which was then reinforced by the discovery of mutations of PTCH1, smoothened homolog (SMO), and other genes related to the HH signaling pathway in sporadic BCC." (PMID 31355203, 2019). "Gorlin syndrome patients carry mutations in Ptch1 and SuFu genes." (PMID 31552081, 2019). "In Gorlin syndrome, a PTCH1 mutation on chromosome 9 was found." (PMID 30423843, 2018). "Notably, of the many mutations in Ptch1 that are known to be associated with Gorlin’s syndrome, three affect these two conserved residues, strongly suggesting the existence of a function that is conserved between the RND family and Ptch1." (PMID 30110910, 2018). "Other important facts of genetic analysis of Gorlin syndrome was that many cases that researchers cannot find mutations in the PTCH1 gene probably due to technical difficulties or existence of mutations outside of the regions analyzed or in genes other than PTCH1." (PMID 28915250, 2017). "These mutations may cause Gorlin’s syndrome with a higher risk of developing MB than PTCH1 mutations." (PMID 26857864, 2016). "PTCH1 is one of the causative genes for nevoid basal cell carcinoma syndrome (a.k.a. basal cell nevus syndrome, OMIM# 109400), which includes OFC and TA as secondary features of its core characteristics, including also jaw cysts, basal cell tumors and skeletal abnormalities." (PMID 27699475, 2016).
Gorlin syndrome (continued). "It was not until 1996, when two independent research groups discovered somatic inactivating PTCH1 gene mutations in a genetic skin cancer disease, Gorlin syndrome, and subsequent discovery of activating mutations of smoothened (SMO) in skin cancer basal cell carcinomas." (PMID 26343727, 2015). "Gorlin syndrome (GS) is an autosomal dominant disorder that predisposes affected individuals to developmental defects and tumorigenesis, and caused mainly by heterozygous germline PTCH1 mutations." (PMID 26544948, 2015). "Rare germline mutations in PTCH1 are known to cause Gorlin syndrome (also called basal cell naevus syndrome) giving carriers a sensitivity to ionizing radiation and an increased risk of jaw cysts, basal cell carcinoma and about 5 % life time risk for developing medulloblastoma." (PMID 26290144, 2015). "Diverse PTCH1 mutations have been identified in Japanese Gorlin syndrome patients." (PMID 26544948, 2015). "Aberrant hyper-activation of this pathway was first identified in Gorlin’s syndrome, where an autosomal dominant mutation in the tumor suppressor gene PTCH1 predisposed patients to basal cell carcinoma (BCC) and/or central nervous system (CNS) malignancy medulloblastoma (MB)." (PMID 25775002, 2015). "Loss-of-function mutations in PTCH1 underlie the molecular cause of Gorlin syndrome (also known as nevoid basal cell carcinoma syndrome), a rare condition characterised by an increased risk of developing various tumours, commonly medulloblastoma, rhabdomyosarcoma and basal cell carcinoma." (PMID 22349813, 2012). "The D362Y mutation seen in this study in sample FICJG, is in the fourth transmembrane domain of PTCH1 and has been previously seen as a loss-of-function germline mutation in a patient with Gorlin syndrome, predisposing to neoplasms (numbered D513Y due to different transcript)." (PMID 21781349, 2011). "Gorlin syndrome is caused by mutations in PTCH1, another gene in the GLI-SHH pathway." (PMID 18435847, 2008). "Indeed, in related Cases 35–36, the pathogenic variant in PTCH1 was identified only in the second pregnancy, as the maternal diagnosis of Basal Cell Nevus Syndrome (BCNS) was still unknown during the first pregnancy." (PMID 41595457, 2025). "Mutations in PTCH1 can cause nevoid basal cell carcinoma syndrome (NBCCS) an autosomal dominant disorder commonly known as Gorlin syndrome." (PMID 37296477, 2023). "Gorlin syndrome, also known as nevoid basal cell carcinoma syndrome, is a hereditary disease that was characterized by Gorlin and Goltz in the 1960s, and is associated with germline mutations in the hedgehog receptor gene PTCH1, along with the exhibition of significant associations with BCC." (PMID 34674729, 2021). "Gorlin syndrome (nevoid basal cell carcinoma syndrome, NBCCS) is caused by heterozygous PTCH1 or SUFU germline mutations." (PMID 32168907, 2020). "Aberrant activation of the Hedgehog pathway is a pivotal defect implicated in BCC, and mutations in Ptch-1 (the Shh receptor) are the leading cause of the inherited form of basal cell nevus syndrome also known as Gorlin syndrome, in which patients may develop hundreds of BCCs." (PMID 32197405, 2020). "Moreover, Gln-iPSCs may serve as a good model to elucidate the mechanism of secondary somatic PTCH1 mutations occurring in Gorlin syndrome-associated tumors." (PMID 32436863, 2020). "However, dysregulation or mutations in HH signaling leads to genomic instability (GI) and various cancers, for example, germline mutation in PTCH1 lead to Gorlin syndrome, a condition where patients develop numerous basal cell carcinomas and rarely rhabdomyosarcoma (RMS)." (PMID 26633513, 2015).